BMP4 (bone morphogenetic protein 4)
Diseases named in the same sentence as BMP4 in open-access papers (continued):
Sharing a sentence is not in itself a finding about the gene and the disease.
breast tumor (7 papers, 2010 to 2024). "We have shown previously that bone morphogenetic protein 4 (BMP4) is lost in more metastatic breast tumor lines and that enforced expression of BMP4 suppresses metastasis." (PMID 38689334, 2024). "In summary, we have identified cholesterol biosynthesis as a major process inhibited by BMP4 and confirmed that statin usage reduces cancer recurrence or metastasis in patients whose breast tumours have a low expression of BMP4." (PMID 39273106, 2024). "Consistent with this, we found that BMP4 expression is lower in basal-like, ER− and high-grade breast tumors, all of which being enriched in BCSC and having the worst prognostic features." (PMID 33649296, 2021). "To assess the requirement for SMAD4 in BMP4-mediated suppression of metastasis, we knocked down SMAD4 in two different breast tumors and enforced SMAD4 expression in a third line with endogenous SMAD4 deletion." (PMID 38689334, 2024). "Finally, we constructed a signature comprising genes that were specifically regulated by BMP4 in the absence of SMAD4 and found that this signature is increasingly represented in high-grade breast tumors and predicts significantly worse overall survival in the Metabric patient dataset." (PMID 38689334, 2024).
tendinopathy (7 papers, 2013 to 2022). "A significant association was reported in a Brazilian mixed-injury cohort for the BMP4 variant (rs2761884) in tendinopathies." (PMID 35629331, 2022). "The BMP4 rs2761884 polymorphism was identified as a risk factor for the development of tendinopathy." (PMID 34366884, 2021). "Furthermore, gene variants of FOXP3, FCRL3, BMP4, and FGF3 and FGF10 as well as FGFR1 were analyzed in connection with tendinopathy in competitive athletes." (PMID 34366884, 2021). "In addition, stronger expression of BMP-2 and weaker expression of BMP-4/7 were observed in and around the chondrocyte-like cells and ossified region in ossified tendinopathy, suggesting the possibility of BMP-2 playing a more vital role in this process." (PMID 33102476, 2020). "Gene and protein expression of TGF-β and protein expression of BMP2, BMP4 and BMP7 were increased in the six studies that compared tendinopathy and healthy tendon tissues from the patella or the Achilles." (PMID 27863509, 2016). "Ectopic expression of BMP-2, BMP-4 and BMP-7 was observed in clinical samples of tendinopathy and collagenase-induced (CI) tendon injury rat model." (PMID 23964681, 2013). "There was ectopic expression of BMP-2, BMP-4 and BMP-7 in clinical samples of tendinopathy and collagenase-induced tendon injury rat model." (PMID 23964681, 2013).
acute lymphoblastic leukemia (6 papers, 2014 to 2022). Leukemia with an acute onset, characterized by the presence of lymphoblasts in the bone marrow and the peripheral blood. "In vitro experimental technologies like flow cytometry and ELISA were utilized to show that acute lymphocyte leukemia cells induce the production of immunosuppressive DCs and favour the generation of M2 by Bone Morphogenetic Protein 4 (BMP4) signal." (PMID 34625124, 2021). "Acute lymphoblastic leukemia cells produce BMP-4 to impair differentiation of macrophages and dendritic cells, and maintain a unique pro-tumorigenic microenvironment." (PMID 32318332, 2020). "Conversely, in acute lymphoblastic leukemia BMP-4 is secreted to drive anti-inflammatory myeloid phenotypes, with dendritic cell immunosuppressive polarization, reduced M1 pro-inflammatory signature, and increased M2 macrophage generation." (PMID 32318332, 2020). "Interestingly, BMP4 resulting from acute lymphoblastic leukemia can upregulate the expression of interleukin (IL)-10 and promote the polarization of M1-like macrophages to the M2 phenotype." (PMID 35832407, 2022). "Interestingly, in acute lymphoblastic leukemia, BMP4 can upregulate the expression of interleukin (IL)-10 and promote the polarization of M1-like macrophages to the M2 phenotype." (PMID 35832407, 2022). "The addition of conditioned media from BMP4-overexpressing acute lymphoblastic leukemia (ALL) cells inhibited the differentiation of moDCs from monocytes." (PMID 34925388, 2021). "The pre-B acute lymphocytic leukemia cell lines 697 and RCH-ACV did not respond to BMP4 treatment with increased pSMAD1/5 levels and thus could not be evaluated for possible inhibition by netrin-1." (PMID 33883596, 2021).
Azoospermia (6 papers, 2015 to 2025). Absence of any measurable level of sperm,whereby spermatozoa cannot be observed even after centrifugation of the semen pellet. "In contrast to our findings, the BMP4 ratio in human NOA patients was increased, whereas another study with men matching our results described lowered BMP4 expression in NOA, but only in comparison to obstructive azoospermia." (PMID 39940876, 2025). "For instance, bone morphogenetic protein 4 (BMP4) enhanced the proliferation of human Sertoli cells by activating Smad1/5 signaling pathway and the ID2/3 pathway in the context of azoospermia." (PMID 41168840, 2025). "In patients with nonobstructive azoospermia, the secretion of inhibin B, Androgen receptor (AR), Bone morphogenetic protein 4 (BMP4), Stem cell factor (SCF) and other growth factors secreted by Sertoli cells is significantly reduced." (PMID 38001535, 2023).
Barrett esophagus (6 papers, 2013 to 2021). Esophageal lesion lined with columnar metaplastic epithelium which is flat or villiform. "The BMP-4 pathway is activated in the oesophageal mucosa in both ulcerative oesophagitis and Barrett’s oesophagus, and this promotes expression of columnar gene markers." (PMID 23297865, 2013). "In Barrett’s esophagus, an early precursor of esophageal adenocarcinomas, the expression of Shh and Ihh is increased in the epithelium, which is associated with stromal expression of the Hh target genes PTCH1 and BMP4." (PMID 23303278, 2013). "Additionally, to determine the effect of BMP4 signaling in a human Barrett’s esophagus (BAR-T) and adenocarcinoma (OE33) cell line." (PMID 27191723, 2016). "Therefore, we determined the expression of BMP4 and several members of the BMP4 pathway in EAC and investigated the effect of BMP4 signaling in a human Barrett’s esophagus (BAR-T) and an esophageal adenocarcinoma (OE33) cell line." (PMID 27191723, 2016). "Bone morphogenetic protein 4 (BMP4) signaling is involved in the development of Barrett’s esophagus (BE), a precursor of esophageal adenocarcinoma (EAC)." (PMID 27191723, 2016). "In disease states such as Barrett’s esophagus, normally absent epithelial Hh ligands are reactivated in metaplastic tissue along with BMP4 expression by mesenchymal cells." (PMID 30120338, 2018).
coloboma (6 papers, 2009 to 2021). An abnormality in which a part of a structure in one or both eyes is missing. "Jnk1−/− Jnk2−/+ mice (lacking activity of members of the Jun N-terminal Kinase, JNK, group of mitogen activated kinases) exhibit coloboma associated with loss of Shh and Bmp4 signaling, and reduced levels of Pax2, while addition of Bmp4 restored Shh and Pax2 expression." (PMID 24412933, 2014). "Notably, the coloboma phenotypes resulting from bmp4 expression induced at 24, 25 and 26 hpf were comparable." (PMID 29593116, 2018). "Our data obtained by timed overexpression of bmp4 in zebrafish embryos clearly indicate that BMP induction has a detrimental effect on optic fissure fusion, resulting in coloboma." (PMID 29593116, 2018). "In addition, a genetic signaling cascade for coloboma centered around PAX2 has been elucidated involving SHH and BMP4 signaling as upstream regulators." (PMID 24412933, 2014).
cyst (6 papers, 2018 to 2025). A sac-like closed membranous structure that may be empty or contain fluid or amorphous material. "Correlation analyses in PCOS rats showed that Bmp4 expression was negatively correlated with the number of preovulatory follicles and positively correlated with atretic cyst-like follicles and Inhba expression." (PMID 41585802, 2025). "To obtain insights into the cyst composition, we performed mass spectrometry of 3D-cysts from the BMP4-guided protocol with either sparse or high IBA1+-cell population at week 4 and 7, respectively." (PMID 35789843, 2022). "Interestingly, while BMP signaling activation is immediately detectable in all cells, squamous morphogenesis (starting approximately 24 hr after BMP4 addition) is initially focal within a given cyst, but then spreads laterally, to form fully squamous amnion cysts by 48 hr." (PMID 39051990, 2024). "The present research work investigated the expression of BMP4 and FGF8 in odontogenic tumors (OT) and cyst as well as developing tooth germs to elucidate their roles." (PMID 30079292, 2018).
holoprosencephaly (6 papers, 2012 to 2025). Holoprosencephaly (HPE) is a complex brain malformation resulting from incomplete cleavage of the prosencephalon, occurring between the 18th and 28th day of gestation, and affecting both the forebrain and face, which results in neurological manifestations and facial anomalies of variable severity. "Interestingly, the double Tsg−/−;Bmp4+/− mutant presents holoprosencephaly, a characteristic of Shh loss of function." (PMID 23028704, 2012). "TSG null: BMP4 homozygous mutant mice are embryonically lethal and display holoprosencephaly (HPE), first branchial arch, and eye defects." (PMID 36361543, 2022). "Accordingly, Shh expression was undetectable in the fore and midbrain of Tsg−/−;Bmp4+/− mutants, explaining the holoprosencephaly phenotype." (PMID 23028704, 2012). "Many of the altered genes, including BMP4, FGF8, SIX3 and LHX2, have previously been associated with PAE and phenotypes of FASD, like defects in heart and corpus callosum development as well as holoprosencephaly." (PMID 40401629, 2025).
lung adenocarcinoma (6 papers, 2014 to 2025). A carcinoma that arises from the lung and is characterized by the presence of malignant glandular epithelial cells. "BMP4 depletion by miR-200 inhibits tumorigenesis and metastasis in lung adenocarcinoma cells and finally FYN promotes cancer progression through epithelial-to-mesenchymal transition." (PMID 31027181, 2019). "In lung adenocarcinoma of our patient cohort and public dataset, FSTL1 expression had positive correlation with BMP4-p-Smad1/5/8-Smad4 expression level and loss of FSTL1, BMP4, and Smad4 expression had a similar trend to predict poor prognosis." (PMID 28852126, 2017). "After revealing the prognostic role of FSTL1, BMP4, and Smad4 in lung adenocarcinoma, we further analyzed their expression correlations." (PMID 28852126, 2017). "In this study, we investigated the mechanism and role of BMP4 depletion by miR-200 in murine lung adenocarcinoma cells." (PMID 26395571, 2015). "Chiou and colleagues showed low expression of FSTL1 and BMP4 in lung adenocarcinoma." (PMID 36756161, 2023). "Therefore, how FSTL1 modulates BMP4-Smad signaling pathway in lung adenocarcinoma should be clarified by further investigation." (PMID 28852126, 2017). "In addition to OLFM4, OLFM1 has been implicated in lung adenocarcinoma and OLFM3 in endothelioma, where it has been proposed to bind to BMP4 and enhance SMAD1/5/8 signaling required for BMP4-induced angiogenesis." (PMID 25364714, 2014). "In addition, we integrated BMP4 into the JAG/Notch signaling pathway and proposed a regulatory loop consisting of JAG2, GATA3, miR-200, and BMP4, suggesting that BMP4 interconnects with various cell signaling partners to induce tumorigenesis and metastasis in lung adenocarcinomas." (PMID 26395571, 2015). "In this study, we investigated the function of BMP4, a TGF-β superfamily member, which is down-regulated by miR-200 in murine lung adenocarcinoma cell lines." (PMID 26395571, 2015). "On the basis of these findings, we propose that BMP4 and BMP receptor antagonists such as DMH2 can be applied to establish prognostic markers or identify therapeutic targets in patients with lung adenocarcinoma." (PMID 26395571, 2015). "When stratified by different histological types, low FSTL1, BMP4, and Smad4 expression retained their trends in predicting poor prognosis in lung adenocarcinoma (LUAD) but not in lung squamous cell carcinoma (SCC)." (PMID 28852126, 2017). "In conclusion, current study revealed that low FSTL1, BMP4, and Smad4 expression significantly predict poor prognosis in lung adenocarcinoma but not in squamous cell carcinoma." (PMID 28852126, 2017). "Lung adenocarcinoma patients with low FSTL1, BMP4, or Smad4 expression had poor prognosis." (PMID 28852126, 2017). "Similar negative correlations between Bmp4 and miR-200 members were also observed in human lung adenocarcinomas and breast invasive carcinomas." (PMID 26395571, 2015). "We determined the relative methylation levels of BMP4 locus in various cancer types and found that its methylation was relatively low in testicular cancer (TGCT), PCPG, and mesothelioma (MESO) but relatively high in thyroid cancer (THCA), PAAD, and lung adenocarcinoma (LUAD)." (PMID 41169612, 2025).
myocardial infarction (6 papers, 2015 to 2025). Gross necrosis of the myocardium, as a result of interruption of the blood supply to the area, as in coronary thrombosis. "Adult human and mouse hearts exhibit constitutive BMP4 expression that increases following myocardial infarction." (PMID 31620450, 2019). "However, administration of FSTL1 reduced ischemic damage and inflammatory response with AMP-activated protein kinase- and bone morphogenetic protein-4-dependent mechanisms in a myocardial infarction model." (PMID 31952198, 2020). "Limited information is available on the role of BMP4 following myocardial infarction." (PMID 31620450, 2019). "For instance, following myocardial infarction, BMP4/Smad1 signaling promotes cardiomyocyte apoptosis through ROS-dependent pathways, and inhibition of BMP signaling confers protection against acute myocardial infarction." (PMID 26317208, 2015). "Unfortunately, experimental studies exploring the role of these BMP4-mediated actions in myocardial infarction have not been performed." (PMID 31620450, 2019).
neuroblastoma (6 papers, 2011 to 2023). Neuroblastoma (NB) is the most common solid, extracranial childhood tumor. "Our transcriptomic analysis did not support activation of DLX2, BRN3A, or NEUROD6 genes as being involved in the BMP4-induced phenotypes of neuroblastoma cells, as previously suggested by studies using BMP2." (PMID 32210188, 2020). "K-means clustering of RNA-seq data of 498 primary neuroblastomas (SEQC) with the 1331 BMP4 DEGs identified 3 patient clusters, corresponding to 3 distinct risk categories." (PMID 32210188, 2020). "Nevertheless, our compelling demonstration of BMP4 protein absence in poorly differentiated and aggressive neuroblastomas, and BMP4’s strong anti-proliferative effect raise the possibility of exploiting BMP4 or agonists of BMP signaling as therapeutic agents." (PMID 32210188, 2020). "In this study, we characterised the phenotypic effects of BMP4 on neuroblastoma cells, demonstrating convergent induction of MSX homeobox transcription factors by Wnt and BMP4 signaling and BMP4-induced growth suppression and differentiation." (PMID 32210188, 2020). "Our Wnt DEGs also showed a correlation with the NOTCH3-ICD regulated transcriptome in neuroblastoma, but to a lesser extent than BMP4." (PMID 32210188, 2020). "In our RNA-seq analysis of Wnt3a/Rspo2-treated neuroblastoma cells, BMP4 was amongst the most highly induced genes (>50-fold) and BMP4 protein was also upregulated, leading us to further analyse global effects of Wnt3a/Rspo2-treatment on BMP/TGF gene sets." (PMID 32210188, 2020). "Given the intersection of Wnt and BMP signaling suggested by our transcriptomic data, we next sought to directly examine the phenotype of neuroblastoma cell-lines treated with BMP4." (PMID 32210188, 2020). "Taken together, our data support Wnt and BMP4 signaling co-operating to regulate the neuroblastoma transcriptome, at least in part by convergence on MSX induction." (PMID 32210188, 2020). "Taken together, our RNA-seq reveals profound effects of BMP4 on the neuroblastoma cell transcriptome, including interaction with Wnt and Notch signaling." (PMID 32210188, 2020). "We previously demonstrated that Wnt/β-catenin signaling can have cell-type-specific effects on neuroblastoma phenotypes, including growth inhibition and differentiation, and that BMP4 mRNA and protein were induced by Wnt3a/Rspo2." (PMID 32210188, 2020). "Consistent with this, decreased BMP4 mRNA in the transgenic Th-MYCN-driven mouse neuroblastoma model, relative to normal ganglia, was also revealed by analysis of a published dataset." (PMID 32210188, 2020). "Exposure to bone morphogenetic protein (BMP)-4 was found to enhance a TrkAhigh/CD15−/CD184− neuroblastoma cellular subset, accompanied by a reduction in doublecortin-positive neuroblasts and of NMYC protein expression in SH-SY5Y cells." (PMID 29051534, 2017). "As illustrated by the longer neurite-like extensions seen in phase contrast microscopy and phenotypic analysis of neuroblast and neural differentiation markers BMP4 treatment appears to promote neuroblastoma differentiation." (PMID 29051534, 2017). "Treatment of N2A cells with BMP4, a component of the Bmp pathway that is known to cross-talk with Wnt signalling in neuroblastoma, led to a 2.3-fold increase in Tcf7l2 and a subsequent 2.1- and 1.9-fold up-regulation in Paupar and Pax6 expression 72 hours later." (PMID 35709096, 2022). "Having established that BMP4 can restrict neuroblastoma proliferation and induce differentiation, we next sought to establish whether BMP4 expression in primary tumors would also reflect a potential tumor-suppressive function." (PMID 32210188, 2020). "Importantly, our analyses strongly support a growth-suppressive function for BMP4 signaling in neuroblastoma." (PMID 32210188, 2020).
neuroblastoma (continued). "Thus, the BMP4 expression pattern in primary tumors aligns with our in vitro functional analyses, strongly suggesting a pro-differentiation and anti-growth role for BMP signaling, particularly BMP4, in neuroblastoma." (PMID 32210188, 2020). "It is interesting to note that in concert with LIF, Bmp4 suppresses differentiation of the neural lineage in mESCs maintained under serum-free conditions supplemented with N2 and B27, which were originally developed to culture a neuroblastoma cell line and hippocampal neurons, respectively." (PMID 21731714, 2011). "We next assessed a second MYCN-amplified (MNA) neuroblastoma cell-line, IMR32, confirming the growth-inhibitory effects of BMP4, with the lowest significant effect observed at 5 ng/mL." (PMID 32210188, 2020). "Similarly, expression of neuroblastoma specific BMP4 upregulated genes significantly correlated with better survival, favourable histology and lower expression of Ki67 proliferation marker in another NB tumour data set, TARGET-NBL." (PMID 32210188, 2020). "As MSX1 has been shown to upregulate Notch signaling, we next examined the links between Wnt, BMP4, MSX1 and Notch in neuroblastoma." (PMID 32210188, 2020). "In order to better define the genes and pathways affected by Wnt and BMP pathways in neuroblastoma cells, we conducted RNA sequencing of IMR32 cells treated with BMP4." (PMID 32210188, 2020). "An immunohistochemical analysis of BMP4 expression in primary neuroblastomas confirms a striking absence of BMP4 in poorly differentiated tumors, in contrast to a high expression in ganglion cells." (PMID 32210188, 2020). "Notch pathway targets and effectors were highly induced in our RNA-seq of IMR32 treated with BMP4, so we first validated a panel of Notch pathway genes, including HES1, MAFB, MAML2 and NOTCH3, confirming a BMP4-Notch signaling pathway in neuroblastoma." (PMID 32210188, 2020).